SAE1 (SUMO1 activating enzyme subunit 1)
Diseases named in the same sentence as SAE1 in open-access papers (continued):
Sharing a sentence is not in itself a finding about the gene and the disease.
glioma (continued). "The mean tumor volume of glioma xenograft was 347 ± 31.5 mm3 in SAE1-overexpressing group after cell inoculation for 20 days, which was larger than the control group volume with 273 ± 36.4 mm3." (PMID 31345225, 2019). "We also used two online databases to analyze the expression level of SAE1 protein in various cancer tissues to verify our results on glioma." (PMID 31345225, 2019). "As a conclusion, a high level of SAE1 expression indicates a high degree of glioma grade, and a short overall survival for glioma patients." (PMID 31345225, 2019). "(A) Longer overall survival for lower grade glioma (LGG) patients with low SAE1 expression level from UALCAN database analysis." (PMID 31345225, 2019). "Generally, more strong levels of SAE1 were detectable in the glioma tissues with higher pathologic grades." (PMID 31345225, 2019). "SAE1 is identified to increase in glioma tissues by a quantitative proteomic dissection, and SAE1 upregulation indicates a high level of tumor malignancy grade and a poor overall survival for glioma patients." (PMID 31345225, 2019). "In order to explore SAE1 roles in glioma cell behavior, lose-of-function of SAE1 was respectively performed in U87 and U251 cells." (PMID 31345225, 2019). "It was consistent to confirm the up-regulated SAE1 at mRNA and protein levels in the glioma tissues." (PMID 31345225, 2019). "To validate the expression level of SAE1 on a certain number of glioma tissues, we further examined SAE1 protein by IHC between 69 HGTs and 12 PBTs." (PMID 31345225, 2019). "About 14 days after injection of SAE1-overexpressing glioma cells in nude mice, palpable tumors were observed approximately with 103 mm3, and subsequently the tumor size was totally monitored for 7 times from then on." (PMID 31345225, 2019). "SAE1-induced glioma development and molecular events were further confirmed in glioma xenograft mice." (PMID 31345225, 2019). "The SAE1 protein showed a much higher expression in 69 gliomas with averagely scoring 6.49 compared with 12 counterparts (p < 0.05)." (PMID 31345225, 2019). "Based on SAE1 downregulation responsible for cell growth inhibition, we further investigated SAE1-mediated glioma cell behaviors and molecular mechanism, including cell cycle distribution and cell cycle relative protein changes." (PMID 31345225, 2019). "The glioma cell growth and migration were evaluated under SAE1 overexpression or inhibition by the CCK8, transwell assay and wound healing analysis." (PMID 31345225, 2019). "SAE1 has also been reported to promote glioma cancer progression through enhanced Akt SUMOylation." (PMID 37705041, 2023). "Both SAE1 overexpression and silencing induced a corresponding increase or decrease in the phosphorylation of SUMOylation and Ser473, thereby promoting or inhibiting glioma cell growth." (PMID 37786890, 2022). "For instance, the expression of SAE1 increases with the level of glioma." (PMID 34267779, 2021). "Moreover, SAE1 enhances SUMO1-modification and activation-associated phosphorylation of AKT, promoting the proliferation and migration of glioma cells." (PMID 34503213, 2021). "SAE1 can increase the SUMOylation of Akt and promote the progression of glioma." (PMID 34267779, 2021). "Therefore SAE1 silencing inhibits glioma cell proliferation and induces cell apoptosis by regulating Akt-involved cell cycle protein level and cell cycle distribution." (PMID 31345225, 2019). "In present study, we systematically identify differential expression proteome between human glioma tissues and its para-cancerous counterparts, from which a marked upregulation protein SAE1 is specially uncovered SAE1 roles in Akt SUMOylation-activated glioma development in vitro and in vivo." (PMID 31345225, 2019). "SAE1 promotes glioma cancer progression via enhancing Akt SUMOylation-mediated signaling pathway, which indicates targeting SUMOylation is a promising therapeutic strategy for human glioma." (PMID 31345225, 2019).
glioma (continued). "We focus on the SUMO-activating enzyme SAE1 roles on glioma and investigate whether targeting SUMOylation on mouse xenograft models can be as potential anti-cancer therapeutics?" (PMID 31345225, 2019). "Meanwhile, we analyzed SAE1 expression and the survival time of glioma patients." (PMID 31345225, 2019). "The higher level of SAE1 means the worse survival for glioma patients." (PMID 31345225, 2019). "On the contrary, SAE1 silence induces an obvious suppression of the SUMOylation and Ser473 phosphorylation of Akt, which inhibits glioma cell proliferation and the tumor xenograft growth through inducing cell cycle arrest at G2 phase and cell apoptosis driven by serial biochemical molecular events." (PMID 31345225, 2019). "We hypothesize the de-SUMOylation is prone to take place when SUMO activating enzyme SAE1 is suppressed, which finally inhibits to glioma cell growth in vitro and in vivo." (PMID 31345225, 2019). "Therefore, we found the expression of SUMOylated Akt and p-Akt are positively correlated with SAE1 level in glioma tissues and cells." (PMID 31345225, 2019). "However, its biological roles of SAE1 in glioma are unclear by now." (PMID 31345225, 2019). "Moreover, SAE1 level is stronger in the higher pathologic grade of gliomas." (PMID 31345225, 2019). "Therefore, SAE1 is a potential candidate marker for prognosis and biotherapy of glioma." (PMID 31345225, 2019). "Therefore, SAE1 activates Akt SUMOylation and Akt phosphorylation (Ser473) in glioma." (PMID 31345225, 2019). "SAE1 upregulation activated AKT SUMOylation-mediated signaling pathways, promoting glioma progression both in vitro and in vivo." (PMID 38801243, 2024). "Previous studies have reported SAE1 as a prognostic biomarker in hepatocellular carcinoma (HCC), triple-negative breast cancer, and glioma." (PMID 37886949, 2023). "Overexpression of SAE1 induces increased SUMOylation and Ser473 phosphorylation of AKT, which stimulates the growth of glioma cells in vitro and in a nude mouse tumor model." (PMID 37786890, 2022). "The expression levels of global SUMOylation, SAE1, AKT, p-Akt, Cyclin D1, CDK2, p21, Bcl-2 and active Caspase-3 were increased in the SAE1-overexpressing glioma tissues." (PMID 31345225, 2019). "These confirmed our conclusion that the expression of SAE1 is positively correlated with Phospho-AKT (p-AKT) and global SUMO-1 levels in glioma tissues." (PMID 31345225, 2019). "SAE1 overexpression induces an increase of the SUMOylation and Ser473 phosphorylation of AKT, which promotes glioma cell growth in vitro and in nude mouse tumor model." (PMID 31345225, 2019). "And the expression distribution of SAE1, SUMO1 and p-AKT in glioma tissues were mainly located in nuclear and cytoplasm." (PMID 31345225, 2019). "Our findings discover that SAE1 overexpression leads to increase of Akt SUMOylation and Akt phosphorylation (Ser473), which increases expression of CDK2, Cyclin D1, Bcl-2 and ultimately to promote glioma cell proliferation and progressin." (PMID 31345225, 2019). "Based on the expression levels of SAE1, Phospho-AKT (p-AKT) and global SUMO-1 levels (SUMO1 conjugates) of the 3 different grades of glioma tissues, generally their levels are relatively lower in the lower pathologic grade I of glioma than the higher grade III and IV." (PMID 31345225, 2019). "SAE1 upregulation enhances cell proliferation, migration by increasing the SUMOylation and phosphorylation of AKT to involve in relevant molecular signaling pathways, which finally accelerates the occurrence and development of glioma in vitro and in vivo." (PMID 31345225, 2019).
hepatocellular carcinoma (9 papers, 2021 to 2024). A malignant tumor that arises from hepatocytes. "While the reported opposite tendency of prognostic influence on gastric cancer and hepatocellular carcinoma by differential SAE1 expression indicated the uncertain association between SAE1 and malignant disease." (PMID 34621746, 2021). "In hepatocellular carcinoma, SAE1 expression is also upregulated, which promotes cancer cell proliferation, invasion, and metastasis by enhancing mTOR sumoylation." (PMID 39742381, 2024). "SAE1 is also closely related to the development of hepatocellular carcinoma, and is helpful for its diagnosis and prognosis." (PMID 35606717, 2022). "Furthermore, high SAE1 protein expression is known to have a strongly significant correlation with metastasis and disease progression in hepatocellular carcinoma." (PMID 37886949, 2023). "For instance, SAE1/2 is significantly upregulated in cancer tissues of hepatocellular carcinoma (HCC) patients, and the survival rate of HCC patients is related to the expression level of SUMO2." (PMID 38566133, 2024). "Upregulated expression of SAE1 was reported in the progression of human cancers, including glioma, and hepatocellular carcinoma (HCC)." (PMID 38351014, 2024).
dermatomyositis (7 papers, 2021 to 2025). Dermatomyositis (DM) is a type of idiopathic inflammatory myopathy characterized by evocative skin lesions and symmetrical proximal muscle weakness. "Inoue et al1 and Jia et al2 described the “angel wings” sign in Asian individuals with antismall ubiquitin-like modifier activating enzyme 1/2 (SAE1/2) antibody-positive dermatomyositis (DM)." (PMID 40353086, 2025). "The final diagnosis was polymyositis in 3 cases, dermatomyositis in 2 cases, immune-mediated necrotizing myopathy in 2 cases, anti-SAE1+ IIM in one case and anti-Mi2b+ IIM in 1 case." (PMID 34944099, 2021). "Interestingly, LPR mice also expressed autoantibodies found in dermatomyositis patients (TIF1γ, Jo1, PL-7, SAE1/SAE2, MDA5, NXP2, mi-2, PM/Scl100) who also demonstrate photosensitivity, and some of these (Jo-1,NXP2, PM/Scl100) were also reduced with MLD." (PMID 40261709, 2025). "However, only a weakly positive small ubiquitin-like modifier 1 activating enzyme (SAE1) antibody was found in serum, which has a sensitivity of 100% and specificity of 99.6% for dermatomyositis." (PMID 40673202, 2025). "These include autoantibodies to Histidyl-tRNA synthetase (Jo-1), Anti-Islet Cell Antigen 512 (IA-2), Tissue Transglutaminase 2 (tTG), Dermatomyositis specific autoantigen Mi-2 (Mi-2), thyroid peroxidase (TPO) and SAE1/SAE2." (PMID 39936155, 2024).
gastric cancer (5 papers, 2021 to 2024). A primary or metastatic malignant neoplasm involving the stomach. "Alternatively, miR‐129‐3p has been reported to inhibit the NHEJ pathway—via the inhibition of XRCC4 SUMOylation—by targeting the SUMO‐activating enzyme SAE1 and repressing the progression of human gastric cancer." (PMID 35000298, 2022).
interstitial lung disease (4 papers, 2022 to 2025). A diverse group of lung diseases that affect the lung parenchyma. "Anti-TIF1-γ (also known as anti-p155/140) is frequently linked to malignancy, anti-MDA5 is strongly associated with clinically amyopathic DM and interstitial lung disease (ILD), anti-NXP2 and anti-SAE1/2 with specific histologic patterns." (PMID 41373880, 2025). "Anti-Mi-2, anti-TIF1γ, anti-NXP2, anti-MDA5, and anti-SAE are characteristic MSA for DM with anti-TIF1γ, anti-NXP2, and anti-SAE1 related to malignancies, and anti-MDA5 associated with severe interstitial lung disease (ILD)." (PMID 39835155, 2024). "Pulmonary interstitial disease was seen in 4 (22.2%, with antibodies for anti-Ro52, anti-MDA5 + anti-Jo1 + anti-TIF1ɣ, anti-MDA5 + anti-SAE1 + anti-NXP2, and anti-cN1A + anti-Ro52) patients, and malignancy was seen in 2 (11.1%) patients (1 with anti-Mi2β and 1 with anti-TIF1ɣ + anti-Mi2α)." (PMID 36045923, 2022).
glioblastoma (3 papers, 2023 to 2025). The most malignant astrocytic tumor (WHO grade IV). "Additionally, SAE1 correlates with glioblastoma grade and affects cell cycle regulators, while SUMOylation stabilizes CDK6, driving the G1/S transition." (PMID 41659205, 2025). "In glioblastoma (GBM), proteins involved in the SUMOylation cascade are upregulated, such as E1 (SAE1), E2 (UBC9) components, and SENP1, promoting tumor progression." (PMID 37415251, 2023). "For example, in glioblastoma (GBM), SUMO machinery components are upregulated, such as SUMO activating enzyme (SAE1), SUMO conjugating enzyme (Ubc9) and SUMO specific protease (SENP1), promoting tumor progression." (PMID 39211047, 2024).
B cell lymphoma (2 papers, 2020 to 2021). "SAE1 knockdown results in synthetic lethality in high Myc–expressing B cell lymphoma." (PMID 32938830, 2020).
colon cancer (2 papers, 2023 to 2024). "SAE1 is highly expressed in colon cancer cells, and inhibiting SAE1 leads to cell cycle arrest, cell apoptosis, and inhibition of cell proliferation in colon cancer cells." (PMID 39742381, 2024). "Inhibition of SUMO1-activating enzyme subunit 1 (SAE1) can block colon cancer cells in the G0/G1 phase." (PMID 37777749, 2023).
lung adenocarcinoma (2 papers, 2023 to 2024). A carcinoma that arises from the lung and is characterized by the presence of malignant glandular epithelial cells. "Overexpression of SENP1 has also been shown to be involved in lung adenocarcinoma progression, and SAE1, UBC9, and SENP3 are remarkably upregulated in lung adenocarcinoma and are associated with poor prognosis." (PMID 37123398, 2023).
lung carcinoma (2 papers, 2023). "To determine the expression patterns of SUMOylation machinery components in healthy bronchi, we surgically obtained the lobar bronchi from patients, who had peripheral lung cancers and underwent pulmonary lobectomy, and performed the immunohistochemistry staining for SAE1/2 and UBC9." (PMID 37393345, 2023).
Obesity (2 papers, 2024 to 2025). Accumulation of substantial excess body fat. "Interestingly, SUMO-activating enzyme subunit 1 (SAE1), which mediates ATP-dependent activation of small ubiquitin-like modifier (SUMO) proteins, was one of the least abundant proteins and TRASH domain-containing protein, which DMBA decreased in lean mice, was increased when obesity was present." (PMID 37856498, 2024).
polymyositis (2 papers, 2021 to 2025). A rare idiopathic inflammatory myopathy characterized by symmetric proximal muscle weakness and elevated muscle enzymes. "A weakly positive serum small ubiquitin-like modifier 1 activating enzyme (SAE1) antibody suggested antibody-negative polymyositis (PM), but serum acylcarnitine analysis indicated increased concentrations of various acylcarnitines, while urine organic acids was normal." (PMID 40673202, 2025).
small cell lung carcinoma (2 papers, 2021 to 2023). Small cell lung cancer (SCLC) is a highly aggressive malignant neoplasm, accounting for 10-15% of lung cancer cases, characterized byrapid growth, and early metastasis. "In small cell lung cancer (SCLC), E1 activating enzyme SAE1/2, the E2 conjugation enzyme Ubc9, and the E3 ligase enzymes were also overexpressed." (PMID 37670258, 2023).
triple-negative breast carcinoma (2 papers, 2021 to 2023). An invasive breast carcinoma which is negative for expression of estrogen receptor (ER), progesterone receptor (PR), and human epidermal growth factor receptor 2 (HER2). "We also identified SAE1 as a potential off-target for Bensazeride; it plays a critical role in regulating triple-negative breast cancer (TNBC)." (PMID 37888725, 2023). "Characteristics of triple-negative breast cancer patients and their SAE1 expression level." (PMID 34621746, 2021).
Arthritis (1 paper, 2020). Inflammation of a joint. "Since SAE1/UBA2 function is predominately dependent on TNF-α–induced activation in vitro, we also determined the effect of GA on joint inflammation in TgTC mice, a human TNF-α transgenic model of arthritis." (PMID 32938830, 2020).
asthma (1 paper, 2023). "Clara cell 10 kDa protein (CC10)-, SAE1-, SAE2-, and UBC9-derived immunosignals were robustly detectable, and the apparent overlapping immunosignals from CC10 and SUMOylation machinery components were readily observed in the BALF cells of children with asthma but not in those with FBA." (PMID 37393345, 2023).
autism (1 paper, 2012). Persistent deficits in social interaction and communication and interaction as well as a markedly restricted repertoire of activity and interest as well as repetitive patterns of behavior. "The SAE1 gene is involved in protein sumoylation process and is shown to interact with the ARX gene, which is involved in Autistic disorder." (PMID 23275889, 2012).
cholangiocarcinoma (1 paper, 2023). A carcinoma that arises from the intrahepatic biliary tree (intrahepatic cholangiocarcinoma) or from the junction, or adjacent to the junction, of the right and left hepatic ducts (hilar cholangiocarcinoma). "TCGA data also showed significantly higher expression of SAE1 in cholangiocarcinoma tissues compared to normal tissues." (PMID 37705041, 2023).
colorectal cancer (1 paper, 2023). A primary or metastatic malignant neoplasm that affects the colon or rectum. "While we have illuminated the potential of SAE-1 in colorectal cancer treatment, a more thorough investigation into the underlying mechanisms is warranted." (PMID 37886949, 2023). "The results of this study established a correlation between high SAE1 expression and poor prognosis in colorectal cancer patients." (PMID 37886949, 2023). "Future research in this area should focus on targeting SAE1 expression via inhibitors or RNAi as a feasible treatment option for colorectal cancer." (PMID 37886949, 2023). "In addition, SAE1 was identified as an independent biomarker of overall survival in patients with colorectal cancer." (PMID 37886949, 2023). "SAE1 knockdown inhibited cell proliferation in vitro and in vivo, decreased the protein expression of cyclin D1, increased PARP protein expression, and promoted radiosensitivity in colorectal cancer cells." (PMID 37886949, 2023).
cutaneous melanoma (1 paper, 2020). A primary melanoma arising from atypical melanocytes in the skin. "It will be interesting to further verify by experiments whether SAE1 gene could be a new prognostic biomarker in cutaneous melanoma." (PMID 32467670, 2020). "In addition, we found that SAE1 could be a new prognostic biomarker in cutaneous melanoma." (PMID 32467670, 2020). "By OSskcm, we found that high expression of SAE1 gene is associated with poor prognosis of cutaneous melanoma, and the prognostic potency of SAE1 gene has not been previously reported in cutaneous melanoma." (PMID 32467670, 2020).
diffuse large B-cell lymphoma (1 paper, 2022). "SAE1 was significantly upregulated in CESC, lymphoid neoplasm diffuse large B-cell lymphoma (DLBC), liver hepatocellular carcinoma (LIHC), pancreatic adenocarcinoma (PAAD), SKCM, and THYM, based on the default cutoff value of the GEPIA2 (|Log2FC| cutoff = 1, and q-value cutoff = 0.01)." (PMID 35859792, 2022).
Hypertension (1 paper, 2023). The presence of chronic increased pressure in the systemic arterial system. "Up until now, the association of other genes, such as ATXN7L3B, LOC646588, EYS, MGEA5, and SAE1, with hypertension had not been extensively researched, but they may also serve as candidates to be further verified." (PMID 36869404, 2023).
liver cancer (1 paper, 2019). An epithelial or non-epithelial malignant neoplasm that arises from the liver. "(B) Longer overall survival for different patients (e.g. Liver cancer, renal cancer and thyroid cancer) with low SAE1 expression level from HPA database analysis." (PMID 31345225, 2019).
Lymph node metastasis (1 paper, 2021). "Lymph node metastasis, tumor grade, LVI, and SAE1 expression were determined to be independent prognostic factors for OS of TNBC patients by multivariate Cox analysis." (PMID 34621746, 2021). "For DFS, tumor size, lymph node metastasis, tumor grade, LVI, and SAE1 expression were identified to be independent prognostic factors in TNBC patients." (PMID 34621746, 2021).